FASTK (Fas activated serine/threonine kinase)
Description:
Phosphorylates the splicing regulator TIA1, thereby promoting the inclusion of FAS exon 6, which leads to an mRNA encoding a pro-apoptotic form of the receptor. [Isoform 4]: Required for the biogenesis of some mitochondrial-encoded mRNAs, specifically stabilizes ND6 (NADH dehydrogenase complex subunit 6) mRNA, and regulates its levels.
Synonyms: FAST
Tractability: PROTAC: ubiquitination databases record sites on it.
Target class: Enzyme; Transferase
Gene: Protein-coding gene on chromosome 7 (151,076,591 to 151,080,866, reverse strand). Ensembl gene ENSG00000164896.
Subcellular location: Mitochondrion matrix (Isoform 4)
Subcellular location (Human Protein Atlas): Mitochondria; Nuclear speckles
Pathways (Reactome):
Metabolism of RNA: FASTK family proteins regulate processing and stability of mitochondrial RNAs
Gene Ontology:
Molecular function: protein binding; protein serine kinase activity; protein serine/threonine kinase activity; Fas-activated serine/threonine kinase activity
Biological process: protein phosphorylation; regulation of RNA splicing; apoptotic signaling pathway; mitochondrial RNA processing; regulation of mitochondrial mRNA stability
Cellular component: mitochondrion; mitochondrial matrix; ribonucleoprotein granule
Genetic constraint (gnomAD): Loss-of-function variants: 28 observed, 55.38 expected, observed/expected ratio (o/e) 0.51, 90% interval 0.37 to 0.69. The upper end of that interval is the gene's LOEUF score, 0.69, which puts it in group 2 of 6, group 1 being the genes least tolerant of losing a copy. Missense variants: 592 observed, 686.53 expected, observed/expected ratio (o/e) 0.86, 90% interval 0.81 to 0.92. Synonymous variants: 325 observed, 294.23 expected, observed/expected ratio (o/e) 1.1, 90% interval 1.01 to 1.21.
Homologues: Orthologues: chimpanzee FASTK (99% identical), macaque FASTK (98% identical), pig FASTK (91% identical), rabbit FASTK (91% identical), dog FASTK (90% identical), mouse Fastk (89% identical), rat Fastk (84% identical), guinea pig FASTK (68% identical), zebrafish fastk (40% identical). Paralogues in human: TBRG4 (21% identical), FASTKD3 (20% identical), FASTKD5 (16% identical), FASTKD1 (15% identical), FASTKD2 (13% identical).
Diseases named in the same sentence as FASTK in open-access papers:
FASTK is named in the same sentence as 18 diseases in open-access papers, as found by Europe PMC text mining. Sharing a sentence is not in itself a finding about the gene and the disease. The quoted sentences say what the papers report.
astrocytoma (9 papers, 2013 to 2025). "Another study identifies FASTK as a direct target of miR-106a-5p, a microRNA whose downregulation in astrocytomas is associated with poor prognosis." (PMID 34768773, 2021). "Accordingly, FASTK was found to be upregulated and positively associated with advanced clinical stages of astrocytoma." (PMID 34768773, 2021). "Using Kaplan-Meier survival analysis, we showed that the low expression of miR-106a-5p or the increased expression of FASTK is significantly associated with poor survival outcome in astrocytoma patients." (PMID 24013584, 2013). "We found that miR-106a-5p expression is significantly downregulated in astrocytoma tissues and is negatively associated with advanced clinical staging, whereas FASTK exhibited the opposite expression pattern." (PMID 24013584, 2013). "In human astrocytomas, miR-106a-5p is downregulated and negatively associated with clinical staging, whereas FASTK is upregulated and positively associated with advanced clinical stages, at both the protein and mRNA levels." (PMID 24013584, 2013). "MiR-106a-5p, a cancer-associated miRNA revealed in the present study, can inhibit proliferation and migration of astrocytoma cells and promote apoptosis by targeting FASTK." (PMID 30381359, 2018). "In our recent work, we proved that miR-106a-5p inhibits the proliferation and migration of astrocytoma cells and promotes apoptosis by targeting FASTK." (PMID 25299073, 2014). "Next, we used Annexin V and PI double-staining FACS analysis to investigate the effects of miR-106a-5p and FASTK on the apoptosis of astrocytoma cells." (PMID 24013584, 2013). "Next, the expression of miR-106a-5p and FASTK was evaluated and stratified according to tumor grade in 84 astrocytoma tissues and in 20 NAT samples." (PMID 24013584, 2013). "In our study, miR-106a-5p directly targets FASTK expression in astrocytoma cells and they play important roles in the disease progression." (PMID 24013584, 2013). "At this concentration, it is obviously that miR-106a-5p can efficiently suppress FASTK expression in astrocytoma cells." (PMID 24013584, 2013). "The knockdown of FASTK induced similar effects on astrocytoma cells as those induced by the overexpression of miR-106a-5p." (PMID 24013584, 2013). "The knockdown of FASTK induced similar effects on astrocytoma cells as those induced by miR-106a-5p." (PMID 24013584, 2013). "Moreover, the same study shows that both the expression of miR-106a-5p and the knockdown of FASTK on astrocytoma cells inhibit cell proliferation and migration and can promote cell apoptosis." (PMID 34768773, 2021). "Furthermore, the over-expression of miRNA-160a-5p is able to enhance apoptosis in astrocytoma cells via decreasing Fas-activated serine/threonine kinase (FASTK), an anti-apoptotic agent." (PMID 35111757, 2021). "We may suggest that the tumor suppressive potential of miR-106a-5p is due to inhibition of FASTK which interacts with TIA1 to mediate Fas-induced apoptosis during astrocytoma pathogenesis." (PMID 24013584, 2013). "Subsequently, we asked whether miR-106a-5p or FASTK expression levels represented specific molecular signatures for subsets of astrocytomas." (PMID 24013584, 2013). "Finally, we investigated the potential function of miR-106a-5p and FASTK in the development and progression of astrocytomas." (PMID 24013584, 2013). "Next, we explored the function of miR-106a-5p and FASTK during astrocytoma progression." (PMID 24013584, 2013). "Thus, FASTK might functionally contribute to astrocytoma progression in roles other than simply as an anti-apoptotic protein." (PMID 24013584, 2013).
breast carcinoma (4 papers, 2022 to 2025). "Further investigating this observation, we were able to show that the loss of PHF5A results in dysregulation of splicing of the anti‐apoptotic gene FASTK, which has already been shown in breast cancer cells." (PMID 39212334, 2025). "We observed that the AS events for COMMD4_AS2, GNAS, MATR3,COMMD4_AS1 and RHOC displayed a significant higher PSI value in cancer patients than in normal samples, while the PSI values were significantly lower for MARK3, POLDIP3 and FASTK in patients with breast cancer." (PMID 36725888, 2023). "In this study, we found a higher PSI value in breast cancer patients than in normal samples for COMMD4_AS2, GNAS, MATR3, RHOC and COMMD4_AS1, whereas the PSI value was lower for MARK3, POLDIP3 and FASTK." (PMID 36725888, 2023). "In breast cancer, PHF5A is essential for cancer cell proliferation, migration, and tumour formation in part through alternative splicing of FASTK." (PMID 37434235, 2023). "We found that METTL3 depletion promoted exon inclusion of the alternative exons of GNAS, MATR3, POLDIP3 and promoted skipping of the alternative exons of COMMD4, MARK3 and the non-m6A modified transcripts FASTK and EXOC7 in both breast cancer cell lines." (PMID 36725888, 2023). "The following genes were reported to be higher expressed in breast cancer samples of cases compared to controls in two different studies but were reported to be lower expressed in another study: SFRP1, ACTR1B, FASTK, TMEM219, NDUFA3, ATP5I." (PMID 36627894, 2022).
lung carcinoma (3 papers, 2021 to 2022). "Our results also showed that the mRNA levels of all FASTK members were strongly upregulated in esophageal, stomach, liver and lung cancers." (PMID 34768773, 2021). "In particular, gene amplification was found for FASTK and FASTKD3 in ovarian and lung cancers, respectively, while increased mRNA levels of all FASTK members were found in esophageal, stomach, liver and lung cancers." (PMID 34888254, 2021). "FASTK and FASTKD3 alterations consisted mainly of amplifications that were seen in more than 8% of ovarian and lung cancers, respectively." (PMID 34768773, 2021).
melanoma (2 papers, 2021 to 2025). A malignant, usually aggressive tumor composed of atypical, neoplastic melanocytes. "FASTKD1 and FASTKD5 were the most frequently mutated FASTK genes, and the mutations were identified in 5–7% of uterine cancers, as well as in 4% of melanomas." (PMID 34768773, 2021). "By performing qRT‐PCR after transfection with siPHF5A for 96 hours, we observed a reduction of the functional form of FASTK (FASTK‐long) as well as an increased expression of the non‐functional, alternative splicing variant FASTK‐short in MelHo and MV3 melanoma cells." (PMID 39212334, 2025).
alcoholic cardiomyopathy (1 paper, 2022). A dilated cardiomyopathy which is associated with consumption of large amounts of alcohol over a period of years. "The deletion of FASTK worsened alcohol damage, whereas cardiac overexpression of FASTK was protective against alcoholic cardiomyopathy." (PMID 36010652, 2022).
autoimmune disease (1 paper, 2025). A disorder resulting from loss of function or tissue destruction of an organ or multiple organs, arising from humoral or cellular immune responses of the individual to their own tissue constituents. "Dysregulation of FASTK members is linked to autoimmune disease, mitochondrial disorders, and cancer, underscoring their role in maintaining human health." (PMID 41099336, 2025).
diabetic retinopathy (1 paper, 2025). "Notably, variants in genes such as nucleoside diphosphate kinase 3 (NME3), LOC728699, and fas-activated serine/threonine kinase (FASTK) have been associated with reduced susceptibility to diabetic retinopathy in certain populations." (PMID 41010507, 2025).
infarction (1 paper, 2020). A localised pathological necrosis of tissue resulting from obstruction of the blood supply usually by a thrombus, an embolus, or vascular torsion. "Consistently, genetic ablation of FASTK exacerbates I/R-induced infarction enlargement and cardiomyocyte loss." (PMID 33585470, 2020).
invasive breast carcinoma (1 paper, 2023). A carcinoma that infiltrates the breast parenchyma. "Additionally, COMMD4_AS1, GNAS, POLDIP3, FASTK, and RHOC AS were significantly associated with METTL3 deletion whereas AS of EXOC7 correlated with both deletion and gain of METTL3 in invasive breast carcinoma." (PMID 36725888, 2023).
mycosis fungoides (1 paper, 2021). Classical mycosis fungoides is the most common type of mycosis fungoides (MF), a form of cutaneous T-cell lymphoma, and is characterized by slow progression from patches to more infiltrated plaques and eventually to tumors. "In the case of mycosis fungoides, overexpression of FASTK was associated with a chromosomal alteration consisting of a gain of 7q36, where the FASTK gene resides." (PMID 34768773, 2021).
myocardial infarction (1 paper, 2020). Gross necrosis of the myocardium, as a result of interruption of the blood supply to the area, as in coronary thrombosis. "TTC/Evens blue staining showed that FASTK replenishment obviously reduced I/R-related myocardial infarction." (PMID 33585470, 2020). "Genetic deletion of FASTK exacerbated I/R-induced cardiac dysfunction, enlarged myocardial infarct size, and increased cardiomyocyte apoptosis." (PMID 33585470, 2020).
myocardial ischemia (1 paper, 2020). A disorder of cardiac function caused by insufficient blood flow to the muscle tissue of the heart. "Utilizing myocardial I/R models, we show that cardiac FASTK expression is markedly inhibited by the reperfusion but not the myocardial ischemia." (PMID 33585470, 2020).
Oral Cancer (1 paper, 2022). "Thus, this review reports theimplication of FASTK proteins in cancer and hence provides a scope to emphasise the role of these proteins in Oral Cancer." (PMID 36518140, 2022).
cancer (10 papers, 2018 to 2025). A tumor composed of atypical neoplastic, often pleomorphic cells that invade other tissues. "In further studies, a member of the Ser/Thr kinase family, Fas-Activated Serine/Threonine Kinase (FASTK) has been linked to cancer development and apoptotic evasion." (PMID 38686058, 2024). "Here, we also provide a complete description of the FASTK genes mutations and the types of cancer where they were found." (PMID 34768773, 2021). "Recently, a pan-cancer analysis showed that FASTK genes are frequently mutated in different cancer types highlighting the potential role of FASTK family members as therapeutic targets." (PMID 34888254, 2021). "Furthermore, expression of FASTK proteins is often altered in cancers, demonstrating potential cancer vulnerabilities and holding promise as novel diagnostic biomarkers." (PMID 41099336, 2025). "Therefore, even though we had found that mutations in FASTK genes are rarely found in cancer, we decided to explore their distribution across multiple cancer types." (PMID 34768773, 2021). "FASTKD1, FASTKD3 and FASTKD5 were the FASTK genes most frequently mutated in cancers." (PMID 34768773, 2021). "In this regard, novel cancer-associated genes might remain to be identified in the amplified regions and, among these genes, FASTK and FASTKD3 could contribute to tumorigenesis in concert with oncogenes in the same amplicons." (PMID 34768773, 2021). "In this cancer type, the loss of PHF5A led to the retention of intron 5 in FASTK, resulting in a non‐functional protein (FASTK‐short)." (PMID 39212334, 2025). "All these data allowed the authors to conclude that in cancer cells, the complex PHF5A–SF3b binds the H3K4me3-containing promoters and then is recruited by the transcriptional machinery facilitating the AS of FASTK to yield the inactive variant." (PMID 35158828, 2022). "It will be interesting to explore how silencing FASTK genes will impact the proliferative and migratory capacity of cell lines derived from these types of cancers, as a first step to explore their potential as therapeutic targets." (PMID 34768773, 2021). "Here, we obtained a pan-cancer overview of the genomic and transcriptomic alterations of FASTK genes." (PMID 34768773, 2021). "With regard to the cancer signaling pathways in which FASTK is involved, it has been described that the efficient splicing of FASTK pre-mRNA requires PHF5A, a key splicing factor in tumor progression." (PMID 34768773, 2021). "Altogether, our results provide a solid starting point for future studies on FASTK genes in cancer research and therapy." (PMID 34768773, 2021). "As reported in the results section, one remarkable finding was the upregulation of all FASTK genes in various types of cancer: ESCA, STAD, LIHC and LUSC." (PMID 34768773, 2021). "We next performed protein-protein interaction (PPI) network analysis to explore the possible relationship between FASTK genes and cancer signaling pathways." (PMID 34768773, 2021). "Accumulated studies have provided evidence that the expression of some FASTK genes is altered in certain types of cancer, in agreement with the central role of mitochondria in cancer development." (PMID 34768773, 2021). "In this study, we investigated the genomic and transcriptomic alterations for all FASTK genes across 33 different human cancer types using data generated by The Cancer Genome Atlas (TCGA) and constructed the protein-protein interaction network for FASTK proteins." (PMID 34768773, 2021). "The expression of the FASTK genes was altered across several cancer types." (PMID 34768773, 2021). "The upregulation of FASTK genes in cancer tissues could potentially contribute to the OXPHOS overload in metastatic cancer cells." (PMID 34768773, 2021). "FASTK genes are rarely mutated in tumor samples and we applied the IntOGen online tool, which did not identify cancer driver mutations in FASTK genes." (PMID 34768773, 2021).
cancer (continued). "In this study, we provide a novel systematic analysis of FASTK gene family alterations in cancer." (PMID 34768773, 2021). "LRPPRC (leucine-rich pentatricopeptide repeat containing), and Fas-activated serine/threonine kinase (FASTK) are protein families playing a major role in mt-mRNA stability and translation and whose dysregulation is related to diverse pathological processes, including cancer." (PMID 34888254, 2021). "As reviewed in the introduction, several studies have previously reported upregulation of FASTK, FASTKD1, FASTKD2 and FASTKD3 in certain types of cancer." (PMID 34768773, 2021). "In this study, our analysis of the TCGA sequencing data revealed that FASTK and especially FASTKD3 amplifications stand out as the most common genetic alterations of FASTK genes across 33 cancer types." (PMID 34768773, 2021). "These interesting results not only reveal the known relationship of FASTK proteins to mitochondrial physiology, but also uncover the particular interaction of FASTK, FASTKD2, FASTKD4 and FASTKD5 with cancer signaling pathways." (PMID 34768773, 2021). "As summarized in the introduction section, several works have revealed the prognostic value of FASTK genes expression in various cancers; however, until now, no genetic alterations of these genes have been described across cancers." (PMID 34768773, 2021). "Finally, we highlight a few in vitro studies that provide mechanistic links between FASTK, FASTKD2 and cancer." (PMID 34768773, 2021). "Finally, the protein-protein interaction network for FASTK proteins uncovers the interaction of FASTK, FASTKD2, FASTKD4 and FASTKD5 with cancer signaling pathways." (PMID 34768773, 2021). "Finally, we provide novel evidence of the PPI network of FASTK proteins, which uncovers the interaction of FASTK, FASTKD2, FASTKD4 and FASTKD5 with cancer signaling pathways." (PMID 34768773, 2021).
tumor (5 papers, 2013 to 2025). "Furthermore, some of these proteins act as tumour suppressors, by proapoptotic and increasing cell survival (e.g., FASTKD3) while othersact as pro-oncogenes and poor prognostic factors (FASTK, FASTKD2, FASTKD4)." (PMID 36518140, 2022). "However, we were unable to confirm some of the previously reported increases in the expression of FASTK genes when the tumor was not included in the TCGA database or had less than 10 matched normal samples." (PMID 34768773, 2021).
infection (1 paper, 2013). The state of being infected such as from the introduction of a foreign agent such as serum, vaccine, antigenic substance or organism. "Considering that sometimes miRNAs might decrease the levels of a specific target mRNA by affecting its stability, we evaluated the FASTK transcript levels at 24 h after infection." (PMID 24013584, 2013).
FASTK also shares sentences with these, for which no sentence is quoted: heart injury (1 paper); uterine cancer (1).